CD86 (CD86 molecule)
Diseases named in the same sentence as CD86 in open-access papers (continued):
Sharing a sentence is not in itself a finding about the gene and the disease.
tumor (continued). "Hyperthermia stimulates the release of tumor‐associated antigens.Hyperthermia significantly increases the proportion of mature DC subtypes (CD11c+, CD80+, CD86+).Hyperthermia increases the CD8+T number in TME.Hyperthermia increases the expression of IFN‐γ and TNF‐α." (PMID 35908281, 2022). "Expression of CD86 on CLL cells is significantly lower than on non-tumour B-cells, and its expression increased on activated B-cells, suggesting that CD86 could be a marker for the activation of CLL cells." (PMID 36213161, 2022). "Importantly, less M1 macrophages (CD86) to M2 (CD206) (M1/M2) ratio was found in the inner region of tumor sections in the IgG group." (PMID 34987649, 2022). "This phenotype could correspond to antigen presenting cells-like hybrid tumour associated neutrophils (APC-like TAN) in which markers for both granulocytes (CD11b, CD66b, CD15) and monocytes (CD33, CD14, HLA-DR, CCR7, CD86, CD20) co-exist." (PMID 36189320, 2022). "However, this tumour-associated population had significantly higher expression levels of CD86 in nsECT4-treated mice, compared to untreated tumour-bearing mice, 11 days after the treatment." (PMID 36551739, 2022). "The combination of cisplatin and 5-fluorouracil also induced a significant release of HMGB1, DC maturation/activation, upregulation of CD80 and CD86 in tumor cell ICD response, and further enhancement of the host antitumor immune response with a favorable prognosis." (PMID 36466838, 2022). "Moreover, tumor cells often show a downregulation of costimulatory CD80/CD86 molecules, which hampers T cells’ activation and contributes to low T-cell function." (PMID 35335881, 2022). "Interestingly, expression levels of MHC I (HLA-A) and costimulatory receptors such as CD86, ICOSLG, and CLEC4A were high in tumor-associated CD206+ Macro_C1QC even compared with tumor-associated cDC1_CLEC9A." (PMID 35503656, 2022). "Reduced HLADR and CD86 are features of immunosuppressive monocytes in cancer, while loss of CX3CR1/CX3CL1 signalling in monocytes and TME can accelerate murine tumour growth." (PMID 36589727, 2022). "All armed OVs, including OV-OX40L, OV-IL12, and OV-OX40L/IL12, increased the expression of the costimulatory receptors CD80 and CD86 on tumor cells, with the strongest upregulation observed in cells infected with OV-OX40L/IL12, followed by OV-OX40L and OV-IL12." (PMID 35715953, 2022). "As a stable ROS, H2O2 could significantly re‐model tumor‐supportive TAMs to anti‐tumor CD80+CD86+ M1 phenotype via down‐regulating M2‐associated CD206 marker and up‐regulating M1‐assoiated‐CD86, CD80, and MHCII markers." (PMID 37323705, 2022). "At 0 h and 1, 4, 7,14, and 21 days after the tumor was resected, the animals were sacrificed, and the brain tissues from the area of resection were analyzed by Western blot to identify the expression levels of myeloid cell markers Iba1, CD86 and Arg1." (PMID 35884700, 2022). "In addition, CD86 expression and the infiltration proportions of M0 and M2 macrophages in tumor tissues were significantly increased." (PMID 35463956, 2022). "Additionally, MS-275–induced tumor inflammation was accompanied by an increase in costimulatory molecule expression (CD86/I-Ab) and antigen-presenting capability." (PMID 35972798, 2022). "Similarly, RH-Δcps have been reported to invade mature macrophages and DCs, increase the expression of CD80 and CD86, and reprogram the suppressed myeloid cells to alleviate tumor immunosuppression." (PMID 36118042, 2022). "Using a combination of functional studies and single cell analysis, a recent murine PDAC study demonstrated that hypoxia inducible factor signaling in cancer-associated fibroblasts drives CD86 and PDL1 expression on tumor associated macrophages to dampen anti-tumor immune responses." (PMID 35664793, 2022). "In addition, cytotoxicity enhanced the expression of the T-cell costimulatory ligands CD70, CD80, and CD86 while stimulating tumor infiltration of APCs, thus improving the antitumor effects." (PMID 36185263, 2022).
tumor (continued). "Notably, cellular analyses indicated that only gDE7 combined with 1MT increased tumor infiltration of monocytic and myeloid antigen-presenting cells expressing higher levels of CD86, an important T-cell costimulatory molecule." (PMID 36405719, 2022). "Studies have shown that NRTUA invasion can convert tumor-associated CD11c+ DCs into an immunostimulatory phenotype, thereby upregulating the expression of IL-12, major histocompatibility antigen I, and T-cell receptor costimulatory molecules CD80 and CD86." (PMID 36118042, 2022). "For example, related studies have shown that the activation of T cells requires costimulatory signals produced by the interaction of CD28 and CD86, which could increase the infiltration of T cells in tumor tissue and prolong the survival time of mice." (PMID 36531226, 2022). "Flow cytometry results further indicated that type I ROS can effectively enhance the percentage of antitumor M1-like tumor-associated macrophages TAMs (CD11b+F4/80+CD86+), which also suggests that CTTPA-G can efficiently remodel the tumor immunosuppressive microenvironment." (PMID 36615526, 2022). "Furthermore, analysis of tumor-infiltrating myeloid cells showed that CD206+C1QC+ TAM express high levels of MHC I and costimulatory receptors such as CD86 and ICOSLG compared with tumor-associated cDC1." (PMID 35503656, 2022). "With the adjustment based on purity, the correlation analysis in STAD revealed that DDR1 was closely linked to most of immune markers in various TIICs, such as CD3E of general T cells, CD86 of monocytes, CCL2 of tumor-associated macrophages (TAMs), and CCR7 of neutrophils." (PMID 35935941, 2022). "Furthermore, a 0.15 overall survival probability was identified for patients with high CD86 gene expression in tumor specimens vs. 0.3 for low expression, and 0.25 vs. 0.17 correspondingly in patients with high and low Arg1 gene expression in tumors." (PMID 35884700, 2022). "The upregulation of Ctla4 and Lag3 was rather specific as no significant changes were observed in mRNA levels of Cd80 and Cd86 (two CTLA4 ligands present in the antigen-presenting (tumour) cells), Tim-3/Galectin-9 (Havcr2/Lgals9), and Pd-l1 (Cd274) immune checkpoints." (PMID 36433941, 2022). "In addition, CD40L expression also increased in vivo cytotoxicity and enhanced anti-tumor immunity through up-regulation of CD80 (B7-1), CD86 (B7-2), and Fas receptor on tumor cells." (PMID 35199207, 2022). "Accordingly, immune‐activated M1‐type macrophages (CD11c+CD11b+F4/80+ or CD86+F4/80+CD11b+) were up‐regulated, and a drop in secretion of immunosuppressive cytokines in G6 was observed (which promotes tumor growth, i.e., TGF‐β and IL‐10)." (PMID 36156442, 2022). "Of note, improved antigen presentation and increased frequency of tumor associated DCs with high expression of CD40, CD80, and CD86 co-stimulatory molecules have been described in response to olaparib, together with enhanced transition of CD8+ T cells to the tumor site." (PMID 36428727, 2022). "However, doxorubicin treatment upregulated M1 marker MHC-II, inducible nitric oxide synthase (iNOS) and CD86, and downregulated M2 marker Arginase 1 and CD206 on tumor-associated macrophages." (PMID 36274066, 2022). "Since a tumor could become more malignant after recurrence or metastasis, the role of CD86 in this stage and the relationship with OS could be further explored." (PMID 36428666, 2022). "The counts of CD163+ cells at the tumour area, but normally higher than that of CD86+ cells." (PMID 34964155, 2022). "Downregulated genes include: 1) Immune system activators, such as CD86; 2) blood tumor suppressors ID2 and KLF4; 3) CEBPB, CEBPB is a BCR/ABL negative regulator gene, which can inhibit the proliferation of BCR/ABL-positive cells, and promote cell differentiation." (PMID 36699453, 2022).
tumor (continued). "In tumor-free mice, Imprime evoked broad innate immune responses (type I interferon signature, mobilization of myeloid cells, dendritic cell and monocyte/macrophage expression of co-stimulatory ligands like CD86, and activation of natural killer cells)." (PMID 35692755, 2022). "Therefore, blocking the interaction between CTLA-4 and CD80/CD86 molecules on the APCs can activate T cells and enhance tumor immunotherapeutic efficacy." (PMID 36733388, 2022). "Pearson correlation coefficients were calculated, and the results indicated that BGN presented the strongest correlations with TIIC markers for monocytes (CD86, CD115), tumor-associated macrophages (TAMs) (IL-10, CCL2, CD68), M2 macrophages (CD163, VSIG4, and MS4A4A) and Tregs (FOXP3, CCR8, TGFβ)." (PMID 35096572, 2021). "The correlations between CD86 expression and tumor immunity were analyzed using the Estimation of Stromal and Immune cells in Malignant Tumours using Expression data (ESTIMATE) algorithm, Tumor IMmune Estimation Resource (TIMER) database, and expressions of immune checkpoint molecules." (PMID 33954112, 2021). "It was determined that DFMO-treated tumors exhibited an increase in F4/80 (macrophage marker), CD86 (a T cell-costimulatory marker) and infiltration of T lymphocytes into the tumor environment as demonstrated by increased CD3, CD4 and CD8 expression in DFMO-treated tumor groups." (PMID 34947972, 2021). "Besides, CD86 expression was correlated with levels of tumor-infiltrated immune cells and expressions of immune checkpoint molecules." (PMID 33954112, 2021). "Strikingly, more M2 macrophages (CD206) and less M1 (CD86) infiltrated into the tumor core in control IgG group, whereas the infiltrating population of M1 macrophages increased in tumor core and M2 macrophages located toward the tumor boundaries after combined treatment." (PMID 34093869, 2021). "In summary, our study demonstrated that CD86/CD163 ratio could effectively stratify stage II-III CRC into two different subgroups with a low and high risk of tumor recurrence and mortality." (PMID 34512652, 2021). "In addition, it has been reported that increased tumor-infiltrating DCs and upregulated their CD86 expression in vivo lead to increased tumor-infiltrating CD8+ T cells and enhanced PD-L1 and MHC class I expression on tumor cells." (PMID 34025668, 2021). "Increased expression of CD86 could indicate a greater propensity to stimulate an anti-tumor T cell response." (PMID 34945011, 2021). "Thus, CD86 was observed to be an unfavorable prognostic factor in tumor progression, OS, and DSS for LGG." (PMID 33954112, 2021). "The binding of CTLA4 to its ligands CD80 and CD86 leads to tumor cell immunosuppression." (PMID 34143198, 2021). "M1 macrophages usually expressed MHC-II, CD68, CD80, and CD86 and had the effect of antitumor and pro-inflammation, while the M2 microphage in the tumor microenvironment could play a role in pro-tumor, immunosuppression, and anti-inflammation." (PMID 35004850, 2021). "At each depth, expression levels of representative biomarkers of cellular apoptosis (caspase-3, termed as Cas-3), ICD (high mobility group box 1 protein, termed as HMGB1), and DC maturation (CD80 and CD86) were examined by immunofluorescent staining of tumor sections." (PMID 33531498, 2021). "Reduced CTLA4 expression on tumor-infiltrating T cells might permit increased expression of CD80/CD86 on Hodgkin-Reed-Sternberg cells, thereby increasing T cell proliferation and modifying the tumor environment." (PMID 33876323, 2021). "To this end, we developed a novel chimeric receptor that can recognize CD80 and CD86 as tumor antigens on malignant B cells by combining the extracellular and transmembrane domains of CTLA4 with the intracellular signaling domains of CD28 and CD3z and explored its potential in cancer treatment." (PMID 33868277, 2021).
tumor (continued). "TAMs with M1 profile usually expressed MHC-II, CD68, CD80, and CD86 and had important antitumor and pro-inflammation function, while the M2 microphage in the tumor microenvironment could play a role in pro-tumor and anti-inflammation." (PMID 34122523, 2021). "SS and IS were both significantly correlated with CD86 expression (r>0.7, P<2.2*10-16), indicating CD86 could serve as a biomarker in tumor purity." (PMID 33954112, 2021). "However, miR-144 or miR-451a promoted the expression of M1-like macrophage markers Marco, Vcam1, MHC II and CD86 in tumor tissues." (PMID 33658044, 2021). "DC maturation in the TME can be promoted by HMGB1 stimulated by preoperative chemoradiotherapy and is accompanied by surface molecule (CD80, CD86, CD208, and LAMP3) expression with anti-tumor functions of tumor-associated antigen presentation, which facilitates effective CD8+ T cell activation." (PMID 33995371, 2021). "Taken together with tumor stage, the stromal CD86/CD163 ratio may serve as a clinically useful tool to improve the prediction of tumor recurrence and guide more appropriate therapies for different risk subgroups." (PMID 34512652, 2021). "Among genes encoding costimulatory molecules, CD70 and CD80 were similarly expressed by FL and normal GC B cells, while CD86 was significantly overexpressed in tumor cells (p = 0.004), and could contribute to the activation of Tfh after binding to CD28." (PMID 33028033, 2020). "In a proof of concept study in mice, the antitumoral activity of DNAhsp65 was correlated with increased percentages of activated lymphocyte (CD4/CD44hi, CD8/CD44hi) infiltration into the tumor mass, enhanced CD86 costimulatory molecule expression in APCs and CD8-T lymphocytes specific lysis." (PMID 35047886, 2020). "Immunogenic cell death induces tumor-associated antigen release and translocation of calreticulin to the tumor cell membrane, which acts as an “eat me” signal to DCs, ultimately activating intratumoral DCs that upregulate the costimulatory molecules CD86 and CD70." (PMID 32355277, 2020). "One of the mechanisms is lacking of co-stimulatory molecules (such as CD80 and CD86), which is caused by the tumor provided inflammatory background and lead TILs become “exhausted”." (PMID 32579541, 2020). "Further flow cytometry analysis of splenic lymphocyte showed that Kejinyan decoction upregulated M1 macrophages and downregulated M2 macrophages, while the total level of macrophages changed little, which was verified by detection of CD68, F4/80, CD206, and CD86 in tumor tissue section." (PMID 32943999, 2020). "Compared with unpulsed group, tumor lysates of RenCa, 4 T1 and CT26 caused remarkable up-regulation of CD80, CD86 and MHC-II expression in DCs, which suggested the maturation of DCs could induced by tumor cells lystates." (PMID 32641056, 2020). "Furthermore, higher levels of CD86 on tumor‐infiltrating cDC2s upon TLR stimulation (R848 or mix) were linked with a worse clinical outcome both for PFS and OS from sampling time." (PMID 33282290, 2020). "It is important to note that IL-12 in G47Δ-mIL12 virus may have played a critical role in activating APCs, since IL-12 is a potent MDSC modulator and shifts splenic MDSCs (isolated from 4T1-tumor bearing BALB/c mice) into CD11c+CD86+ activated DCs." (PMID 32266155, 2020). "In addition, PINK1 expression was more strongly correlated with tumor-associated macrophage markers, such as HLA-G, CD80, and CD86, in LUSC than in LIHC." (PMID 33244455, 2020). "Furthermore, the percentage of CD86+ cells in the primary tumor was the highest in the H-RT+L-TBI group." (PMID 30873170, 2019). "Similarly, DCs also migrate in vitro toward irradiated tumor cells, as seen by the increased expression of the activation marker CD86." (PMID 30873170, 2019). "The expression of CD80 and CD86 on tumor cells or TIICs (especially APCs) may have a bias to suppress or activate the antitumor immune response, respectively." (PMID 31771653, 2019).
tumor (continued). "Notably, CD80 and CD86, which are expressed on both tumor cells and TILs, can interact with CD28 on T cells to activate costimulatory signaling and with CTLA-4 on activated T cells to initiate inhibitory signaling." (PMID 31771653, 2019). "Tumor-resident M-MDSC already expressed high levels of CD86 and remained unaltered upon therapy." (PMID 31694706, 2019). "Therefore, distinguishing CD80 and CD86 expression between tumor cells and APCs is required for a more accurate prognosis prediction in EC patients." (PMID 31771653, 2019). "As expected, the tumor-bearing DCs co-cultured with cryo-thermal macrophages were highly matured, as demonstrated by the increased percentage of CD11c+CD86+MHC II+ DCs along with the higher relative expression of IL-6, TNF-α, CXCL10, IL-1β, IL-12p40, and IL-15 mRNA." (PMID 30833570, 2019). "In an implantable murine model of metastatic osteosarcoma, treatment with anti-PD-L1 antibody resulted in downregulation of PD-L1 expression and upregulation of CD80/CD86 expression on tumor cells, as well as upregulation of CTLA-4 on tumor infiltrating CD8+ T cells." (PMID 31847387, 2019). "However, the percentage of matured DCs (CD11c+CD86+ MHC II +) was significantly down-regulated when DCs were co-cultured with tumour-bearing eosinophils as compared to DCs cultured alone." (PMID 31519961, 2019). "We found that tumour-cell debris after HMME/R837@Lip-augmented SDT could significantly promote DC maturation (CD80+CD86+ DCs) in comparison with HMME@Lip-assisted SDT." (PMID 31048681, 2019). "Similarly, fusion of Tα1 with the tumor homing peptide iRGD results in increased T cell activation and CD86 expression in melanoma and lung cancer." (PMID 31555601, 2019). "Additionally, eCPMV treatment also resulted in significant influx of the CD11b+Ly6G+MHCII+CD86+ tumor infiltrating neutrophils (TINs) that also displayed high expression levels of CD86 and MHCII molecules." (PMID 30974896, 2019). "This hypothesis is supported from our experiments using CD80+/CD86+ Raji tumor models, which provides comparable CD28 costimulation to both CAR-T and AbTCR-T cells." (PMID 30479831, 2018). "However, considering the other markers, such as IL-1β, IL-12, CD86 etc., tested using q-PCR, ELISA and flow cytometry, we confirmed that as a whole Ndrg2−/− macrophages tended to have an M1–like tumor-suppressor phenotype compared with WT macrophages." (PMID 29445150, 2018). "siRNAs blocking the PD-1/PD-L1 or CTLA-4/CD80, /CD86 pathways could reduce the metastasis of tumor cells." (PMID 30564277, 2018). "Similarly, tumor cell downregulation of costimulatory molecules including CD40, CD80, CD86, and ICAM1 have been observed and associated with the rapid progression of various cancers as reviewed in." (PMID 30740111, 2018). "The essential role for CD86 in CD8 CTL-mediated tumor clearance is well-demonstrated." (PMID 30574153, 2018). "Flow cytometry analysis of tumor-associated F4/80+ macrophage cells show that indicated that IL-6 knockout robustly decreased CD86−CD206+ macrophage population and slightly increased CD86+CD206− macrophage population." (PMID 29422647, 2018). "Interestingly, T cells expanded by co-electroporation of OKT3-28BB with CD86 and 4-1BBL showed less differentiated phenotypes, although they still maintained a tumor lytic ability as potent as that of OKT3/IL-2-stimulated T cells." (PMID 28523432, 2017). "Since iTAMs express high levels of CD86, the amplification of the iTAM population may boost T-cell activation and suppress tumor growth." (PMID 29167669, 2017). "The mechanism showed that the combined vaccine could raise CD11c+CD86+ DC, CD11b+F4/80+ MΦ cells and the ratio of Teff/Treg in the tumor microenvironment." (PMID 29263903, 2016).